INS (insulin)
Diseases named in the same sentence as INS in open-access papers (continued):
Sharing a sentence is not in itself a finding about the gene and the disease.
Insulin resistance (continued). "This is not surprising, as fructose-induced metabolic dyslipidemia is usually accompanied by whole body insulin resistance and reduced hepatic insulin sensitivity." (PMID 15723702, 2005). "A useful indicator of insulin resistance can be obtained by multiplying values for fasting blood glucose and plasma insulin concentrations." (PMID 15642120, 2005). "AMPK is known to regulate glucose transport and its metabolism, lower blood pressure, boost liver insulin action, ameliorate insulin resistance induced by free fatty acids, and regulate protein synthesis and forkhead transcription factor FKHR (FOXO1a)." (PMID 16174294, 2005). "A reduction in serum insulin while maintaining fasting serum glucose (p = 0.10) and HgbA1c (p = 0.24) suggests an overall improvement in insulin resistance." (PMID 16359551, 2005). "Telmisartan, but not losartan, significantly (p < 0.05) reduced free plasma glucose, free plasma insulin, homeostasis model assessment of insulin resistance and HbAic." (PMID 15892894, 2005). "Typically, sensitivity to insulin and to glucose ("glucose effectiveness") both diminish, creating insulin resistance." (PMID 16351726, 2005). "Adipocyte insulin resistance, plausibly a down regulation of insulin response due to continued stimulation (from higher dietary CHO), leads to increased lipolysis." (PMID 16288655, 2005). "It is well known that circulating adiponectin increases insulin sensitivity, is decreased in T2D patients, and is negatively correlated with insulin resistance; PPARγ agonists increase insulin sensitivity as well as circulating adiponectin." (PMID 15491498, 2004). "It is due to multiple factors, which the two most important of them being insulin resistance at target organs and impaired insulin secretion from the pancreas." (PMID 15355547, 2004). "During puberty, a certain degree of insulin resistance is normal, and children who are more insulin resistant have decreased SCAT fat gain." (PMID 15530168, 2004). "Through the development of insulin resistance in maternal peripheral tissues and a reduced insulin output, glucose is 'spared' and available for placental uptake and ultimately, fetal demands." (PMID 15352999, 2004). "Perhaps once VAT expands and SCAT depots reach their capacity for storing FAs, then do SCAT adipocytes become insulin resistant, release FFAs, and contribute to systemic insulin resistance and metabolic syndrome." (PMID 15530168, 2004). "The most common reason for the development of hyperinsulinemia (decreased hepatic insulin clearance and/or increased insulin secretion) from insulin resistance is obesity." (PMID 15287987, 2004). "This, in turn, would increase hepatic glucose production, reduce hepatic insulin clearance, and ultimately lead to insulin resistance, hyperinsulinemia, hyperglycemia as well as non-alcoholic fatty liver disease (NAFLD)." (PMID 15530168, 2004). "This diet also induced insulin resistance and impairment of acute insulin response to glucose loading." (PMID 12745668, 2003). "At that point, when a deficit in insulin secretion is combined with a state of insulin resistance, the person develops type 2 diabetes." (PMID 15706798, 1998). "Overall, these findings suggest that insulin-regulated aminopeptidase may serve as a potential biomarker for the identifification of insulin resistance in women with polycystic ovary syndrome." (PMID 41719418, 2026). "Insulin resistance is characterized by inactivation of the insulin-signaling pathway, primarily through serine phosphorylation of the insulin receptor substance, thereby disrupting the phosphatidylinositol 3-kinase/protein kinase B (PI3K/AKT) signaling cascade." (PMID 41590515, 2026). "The enzymatic function of ABHD6 on insulin secretion and insulin resistance is well documented." (PMID 41727161, 2026).
Insulin resistance (continued). "Spearman correlation analyses were performed to evaluate the associations between serum irisin concentrations and a range of metabolic parameters, including insulin, HbA1c, indices of insulin resistance (HOMA-IR, QUICKI), lipid-related indices (LAP, AIP, TG/HDL-C), and waist circumference." (PMID 41596434, 2026). "Indeed, the same study noted positive trends: a tendency towards a reduction in the HOMA-IR index (a marker of insulin resistance) and an improvement in insulin sensitivity specifically at the hepatic level were observed." (PMID 41596351, 2026). "The lower peak insulin levels yielded by intact protein compared to free amino acids may help delay the progression of insulin resistance, thereby benefiting those with T2D or prediabetes." (PMID 41602572, 2026). "Baseline fasting insulin level (proxy for insulin resistance) mediated 20.3% of the total effect." (PMID 42299543, 2026). "On HD − 12, the elevated insulin level may have resulted from increased insulin resistance due to transient hypercortisolemia." (PMID 41536580, 2026). "Furthermore, peripheral insulin resistance modulates insulin-induced FC in the nodes of the DMN and SN13,20." (PMID 41495379, 2026). "Additionally, metBMI residuals correlated more strongly than BMI with insulin resistance, β-cell-linked insulin hypersecretion (Homeostatic Model Assessment of β cell function (HOMA-B), fasting insulin) and impaired glucose tolerance." (PMID 41482560, 2026). "The paper explores shared pathophysiological mechanisms, including impaired insulin signaling, insulin resistance, oxidative stress, mitochondrial dysfunction, chronic inflammation and neuroinflammation, dysregulated glucose metabolism, and gut microbiota dysbiosis." (PMID 41834596, 2026). "On the other hand, due to the key role of insulin signaling in mTOR activation, some studies suggest that omega‐3 therapy may decrease insulin resistance." (PMID 41473401, 2026). "The partial alleviation of diabetic dyslipidemia may be attributed, at least in part, to the improvement in systemic insulin resistance, given insulin's pivotal role in regulating lipid production and secretion." (PMID 41550263, 2026). "In this sense, the study aim is to compare the predictive capacity of the McAuley, QUICKI, SPISE indices, and glucose-insulin ratio against insulin resistance (IR) in Spanish adolescents and to establish reliable cut-off values for these indices in this population." (PMID 41996378, 2026). "Additionally, BMI showed significant positive correlations with fasting insulin (r = 0.267, p = 0.001) and HOMA-IR (r = 0.237, p = 0.003), indicating that greater adiposity was associated with increased insulin resistance." (PMID 41601869, 2026). "Insulin resistance (IR) impairs insulin signaling, which may accelerate brain aging, affect plasticity, and potentially contribute to neurodegeneration." (PMID 41683647, 2026). "T2DM is characterized by a nonautoimmune, progressive loss of β-cell insulin secretion, typically in the presence of insulin resistance." (PMID 41599361, 2026). "Finally, the term “insulin resistance” indicates a possible modulation of insulin sensitivity, integrating the neurochemical effects of fluoxetine with metabolic processes." (PMID 41550142, 2026). "Genetic models of systemic insulin resistance demonstrate impairments in cognition, cerebral blood flow regulation, and emotional behavior, distinct from phenotypes observed in models with brain-specific disruption of insulin signaling." (PMID 41969120, 2026). "In individuals with T2D, where insulin secretion is often blunted and insulin resistance is elevated, the choice of protein both in terms of source (animal vs. plant) and digestive rate (fast vs. slow) may be important in postprandial responses." (PMID 41602572, 2026).
Insulin resistance (continued). "The synergy between both supplements on insulin sensitivity most likely arises from complementary targeting of insulin resistance and reduction in adiposity, since both enhance PI3K/Akt activation in the liver and skeletal muscle and mitigate adiposity and adipose tissue inflammation." (PMID 41596333, 2026). "In addition, beta-C3-KO mice also developed higher fasting serum insulin, suggesting compensatory hypersecretion of insulin to overcome insulin resistance." (PMID 41386533, 2026). "In one of our recent studies, we observed that PreDM and T2DM can have similar BMI and triglycerides yet differ in glycemic burden and in non-insulin-based insulin resistance indices, such as METS-IR and TyG, which track closely with central adiposity measures (BRI, AVI, WWI)." (PMID 41596434, 2026). "In the intervention group, the low-GL kit was associated with stable HbA1c, changes in fasting insulin that were interpreted alongside HOMA-IR (Homeostatic Model Assessment for Insulin Resistance) to assess insulin dynamics, and improved quality-of-life scores." (PMID 42064522, 2026). "Insulin resistance may expose cells, including neurons, to high insulin levels for an extended period, which can negatively impact their function and survival." (PMID 40971458, 2026). "However, individuals with prediabetes are a heterogeneous group and prediabetes is driven by one or more factors such as elevated fat mass, obesity, insulin resistance, impaired insulin secretion and low grade of inflammation." (PMID 41547928, 2026). "Increased circulating levels of insulin or systemic insulin resistance have been shown to alter the blood–brain barrier by downregulating endothelial insulin receptors and decreasing permeability of the blood–brain barrier to insulin." (PMID 41559866, 2026). "In addition, the homeostasis model assessment of insulin resistance (HOMA‐IR) was employed to further evaluate insulin sensitivity." (PMID 41497732, 2026). "Moreover, no clear genotype-related differences were observed in markers of insulin resistance and sensitivity, although XX women exhibited a slightly smaller increase in insulin concentration than RR women during an oral glucose tolerance test." (PMID 42033161, 2026). "Together, our work provides a valuable resource for understanding insulin-regulated PM remodeling in adipocytes, establishes KCC1 and PIT2 as novel insulin-responsive transporters, and supports the idea that insulin resistance involves defects in cell-surface delivery that extend beyond GLUT4." (PMID 41690593, 2026). "Type 2 Diabetes Mellitus (T2DM), characterized by insulin resistance, is increasingly linked to the pathophysiology of both Alzheimer’s Disease (AD) and Polycystic Ovary Syndrome (PCOS) through shared mechanisms involving insulin signaling dysregulation." (PMID 41601981, 2026). "Compared with metformin monotherapy, combination therapy achieved greater reductions in glycated hemoglobin (-1.8 ± 0.9% vs -1.3 ± 0.8%; P < .001), fasting and postprandial plasma glucose, fasting insulin, and homeostasis model assessment of insulin resistance." (PMID 41686569, 2026). "The fatty acids present in the extract may enhance tissue insulin sensitivity by inhibiting alpha‐glucosidase activity, while saponins contribute to the reduction of inflammation and improvement of insulin resistance." (PMID 41549047, 2026). "Adipose tissue-derived EVs impair hepatic fatty acid oxidation, promote steatohepatitis, suppress pancreatic beta-cell insulin secretion, induce skeletal muscle insulin resistance via PPARγ repression, and contribute to endothelial dysfunction and atherosclerosis." (PMID 41977323, 2026). "In participants with PD, EDC-HHA01 supplementation was associated with a statistically and clinically meaningful reduction in HbA1c compared with placebo, supported by concordant improvements in fasting insulin, insulin resistance indices, and reductions in endotoxemia markers." (PMID 42075146, 2026).
Insulin resistance (continued). "In addition, during senescence, the increase in inflammatory mediators can interfere with insulin signaling, thereby contributing to the development of insulin resistance." (PMID 41515459, 2026). "In contrast, wheat flour intake led to an increase in blood insulin levels, suggesting that consumption of wheat flour may contribute to obesity and insulin resistance." (PMID 41574480, 2026). "This would align with others reporting that high circulating insulin and insulin resistance may impair motivation pathways, resulting in heightened stress and food-cue responses." (PMID 41515274, 2026). "Reactive oxygen species could negatively regulate insulin-signaling pathway, further contributing to insulin resistance." (PMID 41590515, 2026). "Moreover, fasting insulin levels and homeostasis model assessment of insulin resistance (HOMA‐IR) were significantly lower in Gpx4Mac‐KO mice than in Gpx4fl/fl mice, further confirming improved insulin sensitivity." (PMID 41524084, 2026). "For cardiometabolic outcomes, EX + IF reduced total cholesterol, triglycerides, low-density lipoprotein cholesterol, and interleukin-6; improved fasting blood glucose, fasting insulin, and homeostasis model assessment of insulin resistance (HOMA-IR); and modestly increased VO2max." (PMID 41883415, 2026). "Insulin sensitivity was estimated by homeostatic model assessment of insulin resistance (HOMA-IR)." (PMID 41665252, 2026). "Moreover, adipose tissue IL-6 levels showed an inverse correlation with insulin sensitivity in obese individuals with type 2 diabetes, and IL-6 released from adipose tissue contributed to hepatic insulin resistance." (PMID 40286055, 2025). "While insulin secretion defects remain the primary mechanism in CFRD pathophysiology, the identification of concurrent insulin resistance may provide important clinical information for risk stratification." (PMID 41300682, 2025). "In conclusion, markers of inflammation and insulin resistance, including IL-6, Hs-CRP, fasting insulin, and HOMA-IR, were significantly associated with BMI-for-age categories, with obese children showing higher levels of both inflammation and insulin resistance." (PMID 40641901, 2025). "Excessive chloride may interfere with K function, leading to IR dysfunction and impaired insulin signaling, thus increasing insulin resistance." (PMID 41235310, 2025). "The authors propose that individuals with well-controlled T1D may maintain normal hepatic glycogen stores and preserve a physiological glucagon-to-insulin ratio, which could protect against both insulin resistance and MASLD development." (PMID 40807122, 2025). "DAL could also contribute to insulin resistance via impaired insulin signaling and enhanced lipogenesis." (PMID 41305607, 2025). "Some reports have shown that LCN2 inhibition promotes the development of diet-induced insulin resistance, while LCN2 administration enhances pancreatic β-cell proliferation increases insulin production and reduces insulin resistance and blood glucose levels in mice with type 2 diabetes." (PMID 39808380, 2025). "It is characterized by insulin resistance, lipid accumulation, impaired glycogen synthesis, and mitochondrial function, which prevents glucose from being transported to the body’s cells for storage in response to insulin stimulation." (PMID 40860658, 2025). "However, the most consistent effect of insulin is to reduce muscle protein breakdown, an effect that is compromised in older adults and those with insulin resistance." (PMID 41356921, 2025). "Notably, insulin resistance, a metabolic state in which tissues fail to respond adequately to insulin, has emerged as a relevant factor in neurodevelopmental disorders." (PMID 40650313, 2025). "Furthermore, alpha-lipoic acid (ALA), an antioxidant with anti-inflammatory, immunomodulatory, and insulin-sensitizing properties, has also been proposed as a potential adjunct therapy due to its favorable impact on insulin resistance." (PMID 41011063, 2025).
Insulin resistance (continued). "However, the liver retains partial insulin sensitivity, as hepatic lipogenesis remains responsive to insulin, even in severe insulin resistance, which contributes to increased FFA influx into the liver." (PMID 39860434, 2025). "In addition, the overexpression of PTEN in mice impairs the insulin signalling pathway, leading to insulin resistance." (PMID 40286074, 2025). "These metabolic disturbances may be attributed to decreased insulin sensitivity and enhanced insulin resistance." (PMID 40977986, 2025). "Some of the mechanisms targeted by phytoconstituents include antioxidant effects; restoration of the functional mass of β cells; reversal of insulin resistance (IR); improved insulin secretion; suppression of glucose digestion and absorption; and promotion of glucose utilization." (PMID 41019174, 2025). "In addition, miR-184, miR-124a2, miR-185-5p, miR-24 and miR-204 have also been connected to the management of insulin production and β-cell proliferation during insulin resistance." (PMID 40565979, 2025). "Although skeletal muscle insulin resistance is very common in adults with obesity, not all adults with obesity are insulin resistant, and factors underlying this difference among a relatively homogeneous cohort of adults with obesity are not well understood." (PMID 39487600, 2025). "A potential explanation is that insulin supplementation in T1DM may inadequately reach brain cells due to insulin resistance." (PMID 41023469, 2025). "As a result, it further disrupts insulin signal transduction and exacerbates insulin resistance." (PMID 41301787, 2025). "Serum insulin is a critical parameter for diagnosing insulin resistance and prediabetes." (PMID 40453670, 2025). "Reduced muscle cell responsiveness to insulin is a characteristic of insulin resistance." (PMID 41355999, 2025). "However, in diabetic patients, impaired function and a decreased number of pancreatic β-cells result in inadequate insulin secretion or insulin resistance." (PMID 40260393, 2025). "Furthermore, the effects of N. sativa oil and metformin on insulin sensitivity, insulin resistance, insulin sensitivity during fasting, ALT, HDL, LDL, TC, TG, and total anti-oxidant capacity were similar." (PMID 40343290, 2025). "When used alongside HFD, which induces insulin resistance by causing obesity, this method effectively simulates the metabolic conditions of type 2 diabetes, eliciting both insulin resistance and compromised insulin production, thereby creating a comprehensive diabetic mouse model." (PMID 39846251, 2025). "In many patients, insulin levels initially rise to compensate for increased insulin resistance." (PMID 41155185, 2025). "Additionally, positive associations were found between higher levels of fecal acetate, propionate, and total SCFA and insulin resistance, body mass index, and fasting insulin levels in obese women." (PMID 39810933, 2025). "Central to its development are insulin resistance and impaired glucose metabolism in peripheral tissues, particularly skeletal muscle, which plays a key role in energy expenditure, glucose uptake, and insulin sensitivity." (PMID 40862756, 2025). "Beta Cell Dysfunction (in pancreatic beta cells, maladaptive responses to chronic stress result in impaired insulin secretion, dedifferentiation, and apoptosis, contributing to the progression from compensation to decompensation in insulin resistance and type 2 diabetes)." (PMID 40564010, 2025). "Group 2 demonstrated a significant reduction in hemoglobin A1c (HbA1c) by 1.90% (p = 0.004), along with a decrease in fasting blood glucose (FBG) by 3.6% (p = 0.009), body insulin by 8.6% (p = 0.009), and the homeostatic model assessment for insulin resistance (HOMA-IR) by 11.11% (p = 0.001)." (PMID 40430469, 2025). "Assuming brain insulin resistance plays a pivotal role in executive function, increasing cerebral insulin sensitivity and availability may improve cognitive performance after preeclampsia." (PMID 40302139, 2025).